CD4 (CD4 molecule)
Diseases named in the same sentence as CD4 in open-access papers (continued):
Sharing a sentence is not in itself a finding about the gene and the disease.
infection (continued). "It is currently not clear to what extent HIV-1 activates CD4+ T cell PRRs during the various stages of infection, and how this would impact infection." (PMID 31919342, 2020). "Subsequent studies involving larger cohorts of SOT recipients have corroborated these observations, showing that reconstitution of HCMV–specific CD4+ and CD8+ T cell responses were required to control infection, whereas patients who only regained CD8+ T cell responses were not." (PMID 32509591, 2020). "Furthermore, studies showed that those individuals with existing CD4 and CD8 T cells that were cross-reactive to the new pandemic virus exhibited less symptoms and less severe disease after infection with 2009 pandemic H1N1 virus." (PMID 32756443, 2020). "Tetramer labeling revealed enrichment of resident memory CD4+ T (Trm) cells in the lower airway; these Trm cells displayed progressive differentiation, downregulation of costimulatory molecules, and elevated CXCR3 expression as infection evolved." (PMID 31815739, 2020). "Variation at I585 was noted in 1 individual with HCV mono-infection (I585V), and 2 HIV/HCV co-infected individuals with CD4 ≥350 cells/mm3 (I585deletion and I585T); however, only the I585V mutation has been evaluated functionally and shown to be associated with dasabuvir resistance." (PMID 32750098, 2020). "The extent of dysbiosis in our study was found to correlate with CD4 nadir and pre-ART CD4 counts, both being measures of the severity of immune collapse during untreated infection which suggests a link between immune function and preservation of microbial community composition." (PMID 32415070, 2020). "Thus, the improved control of parasite growth in the absence of type I IFN signaling was dependent on CD4+ T cells and IFNγ but came at the cost of more rapid development of tissue pathology associated with the acute inflammation generated in the first 14 days of infection." (PMID 32101732, 2020). "However, proliferation of both CD4 and CD8 T cells, as evidenced by Ki-67 staining, occurred in all animals in the first two weeks of infection." (PMID 32946524, 2020). "However, as for the SARS-CoV-2 cross-reactive T cells, the contribution of flavivirus cross-reactive CD4+ and CD8 + T cells in protecting humans from infection with heterologous flaviviruses remains to be resolved." (PMID 33293664, 2020). "In China for example, after the test-and-treat policy became widespread, it became much more difficult to empirically observe CD4+ T-cell count data during natural infection in the absence of ART." (PMID 31964392, 2020). "It is known that infection with one subtype of IAV may induce IAV-specific CD8+ T cells to target different subtypes of IAV6,8,22, or IAV-specific CD4+ T cells to target that specific subtype of IAV8,23." (PMID 33293641, 2020). "Our data demonstrate that the CD4+:CD8+ ratio increases in chickens upon infection and/or HS, without additive effects." (PMID 32612102, 2020). "While natural infection led to high serum antibody levels and a strong proliferative CD4 response, it did not induce a notable IFN-γ response." (PMID 32630694, 2020). "While mutation of the NF-κB–binding motifs moderately impairs proviral expression in immortalized T cells (measured after single round infection of SupT1, Jurkat, and PM1), binding of NF-κB or NFAT to these cis-acting elements are critical for provirus activation in primary systems (CD4+ T cells)." (PMID 32443452, 2020). "Establishing a chronic infection in mouse models is often aided by depleting CD4+ T cells, suggesting a link between the absence of CD4+ T cell help and infections persisting chronically." (PMID 33123174, 2020). "Nevertheless, there was a strong increase in the percentage of cells that expressed CRTAM, EOMES, and T-bet within the CD4+CD44hi T cells in HDAC1cKO-HDAC2HET mice, suggesting enhanced induction of CD4+ CTL features in HDAC1cKO-HDAC2HET Th cells upon infection." (PMID 32102981, 2020).
infection (continued). "This was not the case after infection as a prominent population of donor WT CD4+ T cells co-expressed CXCR5 and PD-1, suggesting a possible Tfh cell fate." (PMID 32348365, 2020). "This shows that the increased Salmonella-specific CD4+ T cells were not due to a baseline increase in naïve precursor T cells in response to thymectomy but was due to an increased response to infection itself." (PMID 32722409, 2020). "CD4 cell and viral load counts have remained the two strongest correlates and surrogate markers of HIV disease progression regularly used in the clinical setting to monitor the infection." (PMID 32216755, 2020). "AgNPs serve through the binding process to gp120, then subsequent inhibition of CD4-reliant on binding, blend, and infection, though the antiviral approach of AgNPs is not entirely understood yet." (PMID 32582621, 2020). "HIV-1 results in productive infection of a small percentage of permissive cells with abortive infection of non-permissive bystander cells in lymphoid tissues (>95% CD4 T cell population)." (PMID 32596261, 2020). "SARS-CoV patients had reactivatable CD4+ and CD8+ T cells 6 years after infection, and this reactivity was specific as SARS-CoV reactivity could be transferred to other T cells through recombinant expression of the cloned TCR." (PMID 33302366, 2020). "Alternative, non-mutually exclusive models proposed the direct infection of resting CD4+ T cells, and naive or effector CD4+ T cells in which the proviral genome is not efficiently transcribed." (PMID 32443452, 2020). "These memory CD4 and CD8 T cells appear important for rapid control of secondary infection." (PMID 33133084, 2020). "CD4+ T cells are the major targets of HIV infection, although DCs may play a large part as they can influence transmission, target cell infection, and antigen presentation." (PMID 32824563, 2020). "In fact, after 30 days of infection the focus of CD4+ T cells reactivity was ZIKV envelope and non-structural antigens." (PMID 32463814, 2020). "Additional studies using purified CD127+ memory CD4+ T cells demonstrated that the lack of productive infection was not due to slower viral replication kinetics or to downregulation of cell-surface CD127 following HIV infection." (PMID 32353080, 2020). "Other entry inhibitors such as ibalizumab, a humanized monoclonal anti-CD4 antibody that inhibits the binding of HIV gp120, might also be highly effective in preventing HSPCs from infection." (PMID 32154191, 2020). "Infection with Msm WT did not increase CD4+ or CD8+ T cell activation, independent of OVA expression." (PMID 32582196, 2020). "In addition, the frequencies of CD4+ or CD8+ T cell PD1 high (PD1 Hi), PD1 intermediate (PD1 Int) both increased significantly at week 5 and 7 post infection." (PMID 32733814, 2020). "In many patients, CD4 and CD8 T cell proliferation (measured by KI67 increase) and activation (detected by CD38 and HLA-DR coexpression) were consistent with antiviral responses observed in other infections." (PMID 32669297, 2020). "In contrast, depletion of CD4+ T-cells (but not macrophages) from non-natural hosts prior to infection resulted in extremely high viral loads, rapid progression to AIDS, and extensive infection of macrophages and microglia." (PMID 32992787, 2020). "However, at day 44 post-infection with L. major, the number of CD8 lymphocytes was significantly higher in LmJ3OE-infected mice compared to LmMC-infected mice, while the number of CD4 lymphocytes was similar between LmJ3OE and LmMC." (PMID 33114674, 2020). "A strong induction of IL-17-producing CD4+ and CD8+ T cells in response to Mav infection in the Msm ΔespG3::mpt64-vaccinated mice, revealing a possible role of IL-17-producing T cells in controlling Mav infection." (PMID 32582196, 2020).
infection (continued). "Treatment with anti-IL-17 mAb did not affect the capacity of CD4+ T cells to respond to infection, as the frequency of cytokine-producing CD4+ T cells was not altered between mice treated with anti-IL-17 or isotype control mAb." (PMID 33298977, 2020). "In another study, it was shown that CD4+ T cells with an inducible regulatory phenotype (CD4+CD25+FoxP3-T-bet+CTLA4high) produced IFNγ and IL-10 in the infection of C3H/HeN mice with a lethal dose of R. conorii and that these cells suppressed proliferation and IL-2 release by CD4+ T cells in vitro." (PMID 33091016, 2020). "Here, almost no cellular expansion of CD4+ T cells was observed in the initial four days post-infection." (PMID 33679697, 2020). "However, in line with the earlier total CD4+ T cell and ELISpot data, there was a significant increase (P = 0.0436) in G-DDF–specific CD4+ T cells in blood on day 10 following infection (mean, 0.108% ± SEM 0.026)." (PMID 31815739, 2020). "Our study showed that there is obvious change in the T-cell subsets in the peripheral blood in the patients, with significantly decreased CD3+T, CD3+CD4+Th, as well as CD3+CD8+Tc NK cell counts, suggesting that the patients undergo significant immune dysregulation after infection with SARS-CoV-2." (PMID 32574334, 2020). "Taken together our results suggest that even if all Msm vaccine strains mediated protection to Mav infection, only the EspG3 disrupted Msm strain overexpressing the MPT64 antigen favored polarization of Mav-specific T cell responses toward CD4+ Th17 and CD8+ Tc17 T cells." (PMID 32582196, 2020). "Our mixed bone marrow chimera experiments demonstrate that the shift toward an effector response in Ifnlr1−/- mice during blood-stage infection is not mediated by direct IFNλ signals on CD4 + T cells, in keeping with observations using similar approaches." (PMID 32407154, 2020). "Agonists of CB2, but not CB1, have been shown to reduce infection in primary CD4+ T cells following cell-free and cell-to-cell transmission of CXCR4-tropic virus." (PMID 32471272, 2020). "However, the analysis of IFNγ, a product of the adaptive immune response (CD4 and CD8 T cells), showed a trend toward reduced expression in immunized IL-6 KO mice after the lethal infection with influenza virus." (PMID 33193346, 2020). "Infection with HIV may engender candidiasis by targeting and depleting Candida-specific CD4+ T cells and otherwise impacting host responses in such a way that selects for fungal virulence." (PMID 32185141, 2020). "The number of CD4+ T cells and CD8+ T cells was reported to peak on day 14 post infection." (PMID 32230738, 2020). "However, in cells with low CD4 levels (~10,000 molecules/cell), a threshold CCR5 level of 10,000–20,000 molecules/cell was required for efficient infection." (PMID 31863725, 2020). "Furthermore, VNPs had significantly higher CD4+ TCM frequencies and counts compared to PuPs despite an almost 10-fold higher duration of infection." (PMID 32194543, 2020). "In particular during early infection, it was indeed shown that the first cells to respond with a significant IFNγ secretion are NK cells, subsequently followed by NKT cells and only later by Th1 CD4+ T cells and CD8+ T cells." (PMID 32218784, 2020). "The importance of T cell responses is demonstrated in HIV patients, where there is a lack of ability to control the infection in patients with reduced CD4+ T cells and also in mouse models lacking CD4+ T cells." (PMID 33384972, 2020). "At day 6 postinfection, the absence of ECM development upon P. berghei K173 infection was consistent with a lower number of brain-sequestered CD4+ and CD8+ T cells than with P. berghei ANKA." (PMID 32265335, 2020). "To determine memory CD4+ T cell subset tropism of C-HIV Envs and whether tropism changes over the first 3 years of infection, we used an in vitro multi-colour flow cytometry assay." (PMID 32762760, 2020).
infection (continued). "Additionally, CD4+ TRM directed against certain pathogens emerge and persist in peripheral tissues following infection, such as influenza-virus-specific CD4+ TRM in the lungs and Leishmania-specific memory CD4+ TRM in the skin." (PMID 32106536, 2020). "It is however important to emphasize the fact that infection-induced IFNγ production does not solely result from the presence of activated CD4+ T helper cells." (PMID 32218784, 2020). "Our data thus indicate the presence of intact mechanisms of CD4+ TCM subset stability in VNPs despite years of viremic infection as opposed to progressive depletion of this subset in PuPs." (PMID 32194543, 2020). "Dual-infection, however, is likely a rare event as it pertains solely to X4-tropic viruses which occur in only 50% of patients at late-stage disease and only a fraction of the EBV-infected B cells express the requisite surface receptors CD4 and CXCR4." (PMID 32576602, 2020). "In comparison to control immunization, these mice developed robust CD4 and CD8 memory T cell, T follicular helper cell, plasma cell, and anti-plasmodium antibody responses, were partially protected from initial infection, and were completely protected from a subsequent re-infection." (PMID 32244916, 2020). "Finally, we detected phenotypic changes in CD4 and CD8 T cells, implying some involvement of the adaptive immune system in controlling infection." (PMID 32747639, 2020). "The CD4+/CD8+ ratio was higher in patients with secondary infection compared with non-infected cases during the first 7 days, but the CD4+/CD8+ ratio was markedly decreased by 28 days." (PMID 32296650, 2020). "The role of CD4+ T cells in immunity for Cr is well known, but there are relatively fewer studies on the role of cytotoxic T cell (CD8+ T cell) and Treg cell in Cr infection." (PMID 32230738, 2020). "Nonetheless, similar to the adoptive transfer of immune CD8+ T cells, the transfer of immune but not naive CD4+ T cells into C3H/HeN mice was protective against a normally lethal infection with R. conorii." (PMID 33091016, 2020). "Our results indicate that total CD4 T-cell counts as well TEM and TFH declined at the initial steady state of infection in the spleen, whereas a slight increase in the number of CD4 T cells derived from axillary and inguinal LNs compared to healthy individuals was observed." (PMID 31723251, 2020). "Furthermore, in human CL, CD4+ Th1 immune response with the production of IFN-γ, TNF-α, and IL-12, as depicted in, has been correlated with infection control via macrophage activation and parasite destruction." (PMID 32656269, 2020). "We also provide evidence that TH1 cytokine+ CD4 T cells are flexible in their expression of lineage markers irrespective of Mtb and SM infection status." (PMID 32117277, 2020). "Such enhanced inflammatory response can result in more severe pathology as observed in the infection with R. typhi upon the adoptive transfer of immune CD4+ T cells into C57BL/6 RAG1-/- mice where CD4+ T cells, when transferred late in the infection, promote MΦ-mediated inflammation in the brain." (PMID 33091016, 2020). "Thus, it is very likely that uninfected CD4+ T cells are activated and participate in host defense against MDV after infection or vaccination." (PMID 32080753, 2020). "The role of CD4+ T cells in Ehrlichia infections has not yet been clarified as CD4 knockout (KO) mice have been reported to be capable of resolving E. chaffeensis experimental infection." (PMID 33233869, 2020). "The CD4+ T-cell counts at baseline were not significantly different between single infection, double infection and triple infection (median 429.5, 376 versus 290 cells/μl; P > 0.05)." (PMID 32038599, 2020). "For example, HERVK13-int was up-regulated in 10 human virus data sets, including HIV-infected activated CD4+ T cells (HIVactivated CD4+T cell) and resting CD4+ T cells (HIVresting CD4+T cell), IAV, and HSV-1, which have already been shown to express HERVK during infection." (PMID 31964680, 2020).
infection (continued). "It was therefore puzzling that a large body of literature describes human astrocyte infection, despite the fact that these cells do not appear to express CD4 or CCR5, at least in culture." (PMID 32354203, 2020). "The secretion of IL-10 from CD4+ CD25− FOXP3− cells in the initial phase may suppress the Leishmanicidal mechanisms of macrophages, which supports the establishment of infection." (PMID 32849534, 2020). "A significant decrease of the absolute numbers of circulating lymphocytes was found in old NHPs at the steady‐state (absence of recent/current infection or vaccination) mainly affected by the selective drop of CD4 T‐cell counts." (PMID 31840398, 2020). "Our results also indicate that naive virus-reactive CD4+ T cells start to primarily replicate in the CNS and deep cervical lymph nodes rather than in the periphery as early as 2 d post infection." (PMID 33086489, 2020). "In support of this hypothesis, CD8+ effector memory cells were expanded in the draining lymph node whereas CD4+ Tem cells remained at lower levels and like those induced by the HSV-1(F) infection." (PMID 32027675, 2020). "While control mice (CnH99-infection alone) did not lose weights between week 3 and 4, 80% of C-IRIS mice (CnH99 + CD4+ T) approached the humane endpoint (∼30% weight loss) within 12 days after T cell transfer." (PMID 33133067, 2020). "The abortive infection resulted in a long-lasting immunity in Mdr2−/− mice against infectious SPZ where neutrophils and IL-6 appear as key effector components along with CD8+ and CD4+ effector and central memory T cells." (PMID 33329563, 2020). "CD4+ T cells, CD8+ T cells, and NK cells were examined for cytokine production during Phase 1 (5 and 7 DPI), Phase 2 (10 and 14 DPI), and Phase 3 (90 DPI) of infection." (PMID 31963302, 2020). "CD4 and CD8b showed no significant variation between infection subtype profiles in mRNA expression in unstimulated koala PBMCs." (PMID 33316950, 2020). "During acute infection, HCV-specific CD4+ T cells are primed and initially expand to form a multispecific and multifunctional CD4+ T cell response, irrespective of the outcome of infection." (PMID 32781731, 2020). "Subsequent work found that TLR7 promotes a rapid wave of IL-10 secretion from CD4 T cells that inhibits early FV replication as well as a non-neutralizing IgM response within days of infection." (PMID 33202596, 2020). "Having a look at the CD4+IFNγ+TNFa+IL-2+ triple producers, a drastic increase with age was visible independent of infection history (right)." (PMID 32849561, 2020). "ESAT-6 specific CD4 T cells were only detectable at week 6 after aerosol infection without differences between the groups." (PMID 32673357, 2020). "For our group of poor responders treated during AHI, CD4/CD8 ratio at baseline was higher than in participants treated during chronic HIV infection, reflecting less immune dysregulation at the earliest stages of infection." (PMID 32949118, 2020). "Although we did not observe a productive infection in CD4+ primary T lymphocytes, we observed virus-like particles in these cells by electron microscopy." (PMID 32558639, 2020). "Interestingly, we could recapitulate the in vitro finding by demonstrating a decreased frequency of T-bet+ CD4+ T cells when wildtype-infected were compared to Δhla-infected animals, while significantly increased frequencies of RORγt+ CD4+ T cells were observed upon infection with both strains." (PMID 32849537, 2020). "However, LCs also express the HIV entry receptors CD4 and CCR5, which mediates the fusion of gp160 and leads to productive infection of the cell." (PMID 32824563, 2020). "Although NL-DT5R established a productive infection and elicited humoral responses against all of the HIV-1 structural proteins in PTMs, it did not cause CD4+ T cells depletion or disease." (PMID 32477302, 2020).